HPSE (heparanase)
Diseases named in the same sentence as HPSE in open-access papers (continued):
Sharing a sentence is not in itself a finding about the gene and the disease.
infection (34 papers, 2013 to 2025). The state of being infected such as from the introduction of a foreign agent such as serum, vaccine, antigenic substance or organism. "Similar findings were reported for porcine reproductive and respiratory syndrome virus (PRRSV) whose infection causes upregulation of cathepsin L and heparanase, leading to a decrease of cell surface HS chains and, in turn, promoting viral release." (PMID 36012353, 2022). "Using a genome-wide analysis of HPSE-deficient cells, we aimed to define the factors and related pathways that make these cells naturally resistant to infection." (PMID 33621216, 2021). "The identification of viral factors implicated in infection induced HPSE upregulation is important." (PMID 36298711, 2022). "During ocular HSV-1 infection, it has been shown that upregulation of HPSE at the nucleus caused decreased interferon signaling and increased NF-κB activation, resulting neighboring cells to be more susceptible to infection and increased pro-inflammatory factor production." (PMID 30555321, 2018). "A possible caveat is that cells overexpressing constitutively active HPSE, given its emerging pro-viral/pro-microbial roles, may be more prone to death due to high susceptibility to infection combined with the inflammatory conditions that its constitutive expression may generate." (PMID 34578329, 2021). "In this section, we summarize the major findings in virus-heparanase-1 interactions, as well as discussing the possible targeting of the enzyme by specific compounds in order to block infection." (PMID 36680276, 2023). "To observe the changes in immune response from primary to secondary infection, we infected HPSE+/+ andHPSE−/− mice with HSV-1." (PMID 37115924, 2023). "HSV-1–infected HPSE+/+ animals create a stronger immune response during secondary infections compared to the primary infection." (PMID 37115924, 2023). "Pharmacological inhibition of HPSE by OGT-2115 in HPSE+/+ mice exhibited similar protection levels against secondary infection of HSV-1." (PMID 37115924, 2023). "Heparanase-1 is also involved in the infection cycle of RNA viruses, such as the positive single stranded RNA virus DENV, causing the most prevalent mosquito-borne disease in humans, which is a major public health issue worldwide." (PMID 36680276, 2023). "CREB3-transfected HCE cells showed significantly higher export of HPSE upon infection than wild-type cells." (PMID 35746643, 2022). "This connection is also supported by the fact that γ 34.5 is expressed during later stages of infection and HPSE upregulation coincides with its expression." (PMID 36298711, 2022). "Heparanase was up-regulated by PRRSV during the late-stage infection, where heparanase knockdown suppressed PRRSV release while its overexpression enhanced." (PMID 35958155, 2022). "Recent evidence demonstrates that host-encoded HPSE is upregulated and required for the release of viral progeny after herpes simplex virus 1 (HSV-1) and 2 (HSV-2) infection." (PMID 36012353, 2022). "The involvement of heparanase, acting by lowering N-sulfation and iduronic acids units of HS chains, thus reducing infection, has been shown in different cell lines infected by RSV." (PMID 34207476, 2021). "With a focus on cellular responses to infection, we show here that HPSE acts beyond its known endoglycosidase activity as a potent regulator of the signal transduction phase of cellular defense." (PMID 33621216, 2021). "Multiple viruses including Herpes Simplex Virus-1 (HSV-1), cytomegalovirus, and Dengue virus have been shown to hijack heparanase expression to facilitate infection." (PMID 34681753, 2021). "Fusobacterium nucleatum, which induces periodontal disease and can lead to oral carcinoma, was shown to increase heparanase expression upon infection in vitro." (PMID 34681753, 2021). "Further understanding of the modulation and role of heparanase during these infections is required to verify heparanase as a viable target." (PMID 34681753, 2021).
infection (continued). "In the case of HSV, it was recently discovered that upon infection the expression of heparanase enzyme is up-regulated via NF-kB mechanisms, which aid in cleaving off the HS/3OS HS chains resulting in virus release, supporting viral pathogenesis." (PMID 30555321, 2018). "Accordingly, future studies will include HS neutralization by intravaginal administration of soluble recombinant Mac-1 or heparanase to CVVC-S mice during infection to improve PMN antifungal activity." (PMID 28292981, 2017). "Reduction of matrix metalloproteinase and HPSE activities dramatically reduced virus release from the ECM, which resulted in the loss of viral uptake and infection of human keratinocytes." (PMID 28927006, 2017). "Increased corneal expression of this molecule has also been reported during infection, most likely due to HPSE-positive infiltrating cells." (PMID 29379222, 2017). "HPSE+/+ mice shed more virus at 2 days post-infection (dpi)." (PMID 37115924, 2023). "During primary infection, most immune cell types were similar between HPSE+/+ and HPSE−/− mice." (PMID 37115924, 2023). "Indeed, heparanase-1 has been described to help leukocytes to traverse blood vessel walls on their way to infection sites." (PMID 36680276, 2023). "Subsequently, it was found that the post-infection increase in heparan sulfate expression is transient as HSV-1 positively regulates heparanase (HPSE) to remove heparan sulfates allowing virus release, whereas knockdown of HPSE drastically decreases its release." (PMID 36077240, 2022). "However, the blots revealed a marked decrease in the relative expression of CREB3 and the unfolded protein response (UPR) regulator, GRP78, in HPSE knockout cells compared to wild-type cells at 3, 6, 9, 12, and 24 h post-infection." (PMID 35746643, 2022). "Indeed, we and others showed that both heparanase and Angpt-2 levels are elevated during the acute infection." (PMID 35951203, 2022). "Interestingly, in line with infection efficiency, we observed a significant increase in HPSE expression in podocyte supernatants infected with a higher viral dose, but not in those infected with a lower dose or UV–inactivated HTNV." (PMID 35336857, 2022). "Heparanase is upregulated during infection with several types of viruses." (PMID 34681753, 2021). "Immunoblotting of E-cadherin was also performed to assess whether changes to the total protein levels were made as a result of infection or upregulation of HPSE and whether this contributes to the potentiation of β-catenin." (PMID 34749529, 2021). "However, the opposite trend was observed in HPSE knockout cells where the expression level of p-GSK-3β (Ser9) was reduced following infection." (PMID 34749529, 2021). "To check whether HS on cell membrane may have influenced IBV S protein binding to HSPA8, we performed the binding blocking assay and infection inhibition assay based on removal of HS by using heparanase." (PMID 32765462, 2020). "During homeostasis, HPSE expression and its endoglycosidase activity are tightly regulated; however, under stress conditions, including infection, its expression may be upregulated, which could contribute directly to the onset of several disease pathologies." (PMID 28927006, 2017). "This newly-found role of HPSE describes two different modes during infection of a cell by HSV-1." (PMID 28927006, 2017). "We previously demonstrated that higher levels of the tetrad heparanase, TF, TFPI, and TFPI-2 are present in hypercoagulable states as malignancy, recurrent abortions, pregnancy, and infection, mainly in the tissues’ microcirculation." (PMID 39766213, 2024). "HPSE exerts its enzymatic activity by cleaving HS moieties from cell surface, which negatively affects HSV-1 entry during a primary infection." (PMID 37115924, 2023). "In another report, in which heparanase-1 was shown to promote HSV-2 release, the overexpression of heparanse-1 clearly increased the infection and virus release from vaginal epithelial VK2 cells." (PMID 36680276, 2023).
infection (continued). "While the expression at 0 h in both HPSE wild-type and knockout cell types was very low, CREB3 expression increased immediately post infection in both cell types." (PMID 35746643, 2022). "This review outlines the role of HPSE and SDC-1 as newly assigned host factors that facilitate HSV-1 release during a lytic infection cycle." (PMID 36298711, 2022). "Of note is the upregulation of a multifunctional host protein, heparanase (HPSE), following infection, which serves as a mediator in HSV-1 replication." (PMID 34749529, 2021). "Inhibition of syndecan-1 shedding by MMPs, ADAMs, and/or heparanase greatly reduces cellular uptake of HPV serotype 16 and subsequent infection." (PMID 34207476, 2021). "Following infection with HSV-1, differences in the transcriptomic landscape of wild-type and heparanase knock-out cells were observed." (PMID 34681753, 2021). "Finally the results of binding blocking assay and infection inhibition assay showed that recombinant HSPA8 protein and antibody to HSPA8 could inhibit IBV Beaudette strain infection of Vero cells that were treated with heparanase to remove heparan sulfate from the cell surface." (PMID 32765462, 2020). "Consistently, up to 90% (25 out of 28) of the ISGs (except for family with sequence similarity 46, member C (FAM46C), heparanase (HPSE), and SUN2) exerted significant facilitation in THP-1-Mφs within 48 h infection of H37Rv." (PMID 30717477, 2019). "Expression levels of HPSE mRNA positively correlated with marked proteinuria and urinary protein level, at 24 h post infection; this could be important to the loss of negative charged moieties in the glomerular basement membrane, aiding to the pathogenesis of RSV." (PMID 28927006, 2017). "Of note, there was a significant difference of heparanase levels between the strains of infection, with a significant higher heparanase level and activity in patients with Gram-negative septic shock." (PMID 27699168, 2016). "Our results suggest that HPSE dysfunction increases the severity of disease during reinfection and that prior infection with HSV-1 fails to protect the animals from ocular disease manifestation unless HPSE is silenced or its pathological functions are pharmacologically inhibited." (PMID 37115924, 2023). "In line with this evidence, HPSE−/− mice were observed to show less immune infiltration even with higher cytokine expression, which may confirm the importance of HPSE in immune cell migration to the site of infection." (PMID 37115924, 2023). "It is worth highlighting that HSV-1 particles can be mobile at the surface of CHO and HaCaT cells without the cooperation of heparanase during the recruitment and early attachment prior to infection, and that the interaction with HS and CS is enough to create mobility." (PMID 36016458, 2022).
kidney diseases (18 papers, 2011 to 2025). "More recent studies have highlighted the pathogenic role of heparanase-mediated HS cleavage in renal disorders." (PMID 36979689, 2023). "Additionally, heparan sulfate degradation by heparanase has been linked to glomerular and tubular/interstitial injury in several kidney disorders." (PMID 36979689, 2023). "Inhibition of HPSE and/or HPSE deficiency is beneficial in experimental lung and kidney diseases." (PMID 33123154, 2020). "Upregulation of heparanase expression and/or activity was reported in patients with various kidney diseases and after kidney transplantation." (PMID 36293542, 2022). "Emerging evidence indicated that glomerular heparanase is engaged in several renal diseases primarily in DN and the levels of albuminuria is significantly associated with the heparanase over-expression in DN." (PMID 28994624, 2017). "Experimental evidence supports the idea that heparanase-inhibiting heparin-derived agents and glycosaminoglycans favorably affect primary and secondary renal diseases, likely via inhibition of heparanase enzymatic activity." (PMID 23028487, 2012). "However, the involvement of heparanase and α2-macroglobulin in other renal diseases leading to proteinuria has been documented." (PMID 38426210, 2024). "The induction of heparanase expression by IR in kidney cells both in vitro and in vivo, together with the known contribution of heparanase to the pathogenesis of several kidney disorders other than RN, led us to hypothesize that the inhibition of heparanase may prevent the progression of RN." (PMID 36979689, 2023). "Although the participation of HPSE in a number of physiological processes (e.g., embryo implantation and development, hair growth, and inflammatory processes), researchers nowadays are mainly focusing on its involvement in pathological conditions including tumor progression and renal diseases." (PMID 26040666, 2015). "On the other hand, it is known that heparanase regulates sFlt-1 release, and correlations between circulating eGC components and sFlt-1 levels have already been described in an animal model of renal disease but not in preeclamptic women." (PMID 36982455, 2023). "Emerging evidence suggests the involvement of heparanase in diabetic and nondiabetic proteinuric kidney diseases." (PMID 28388547, 2017). "In addition, HPSE has been shown to play several important non-enzymatic roles in kidney diseases and renal fibrosis." (PMID 35173145, 2022).
hematological malignancies (5 papers, 2014 to 2023). "Association of heparanase, Sulf1, and Sulf2 in solid tumors and hematologic malignancies." (PMID 25105093, 2014). "SNP analysis of the HPSE gene in CMV-seropositive patients with hematological malignancies revealed a significant correlation between the incidence of ALL and insulator rs4426765 SNP." (PMID 34943994, 2021). "Genotype and allele frequency analysis of 5 HPSE gene SNPs (rs4693608, rs4693084, rs4426765, rs28649799 and rs4364254) in all 523 patients with hematological malignancies did not reveal a correlation with CMV seropositivity." (PMID 34943994, 2021). "The study was the first evaluating a HS mimetic/heparanase inhibitor in a hematological malignancy." (PMID 30413079, 2018).
kidney (3 papers, 2011 to 2019). "HPSE inhibition would therefore constitute a new pharmacological strategy to reduce acute kidney injury and to prevent the chronic pro-fibrotic damage induced by I/R." (PMID 30546836, 2018). "Furthermore, the 5-year survival rate is higher for patients with negative HPSE expression, and significant correlations were reported between HPSE expression and liver metastasis." (PMID 31001480, 2019).
Bacterial infection (2 papers, 2021 to 2023). "Bacterial infection has also been shown to modulate heparanase expression." (PMID 34681753, 2021). "Given this, heparanase may also play a role in the pathogenesis of these bacterial infections." (PMID 34681753, 2021). "Dengue non-structural protein 1 (NS1) directly induces glycocalix shedding of lung endothelium through the upregulation of cathepsin L, endothelial sialidases, and heparanase through TLR-4, similar to bacterial infection via LPS." (PMID 36671689, 2023).
benign tumors (2 papers, 2015). "In other words, HPSE would be partially activated, as confirmed by the virtual absence of the 50 kDa HPSE isoform in normal thyroid sample and, thus, both HPSE and especially HPSE2 would remain preferentially in colloid in the benign tumors and normal thyroid tissues." (PMID 26488476, 2015).
gastrointestinal tumor (2 papers, 2015 to 2019). "Furthermore, patients were grouped according to their gastrointestinal tumor types and the heparanase isoforms were quantitatively analyzed in each subgroup, in relation to the control group." (PMID 25351637, 2015).
vasculopathies (2 papers, 2011 to 2012). "Collectively, these results imply that continuous exposure to high levels of heparanase in the circulation may contribute to the development of diabetic-associated vasculopathies." (PMID 21364956, 2011). "Continuous exposure to high levels of heparanase in the circulation may thus contribute to the development of CKD-, and transplantation-associated vasculopathies." (PMID 23028487, 2012).
head and neck tumours (1 paper, 2014). "Heparanase expression correlates with both invasiveness of HNSCC cell lines and the metastatic potential of head and neck tumours 23,24,26–28, emphasizing a role of the enzyme in HNSCC aggressive behaviour." (PMID 24286246, 2014). "In agreement with this notion, in head and neck tumours heparanase mRNA/protein are highly expressed, whereas normal epithelium expresses little or no heparanase, 23–27." (PMID 24286246, 2014).
retinopathy (1 paper, 2012). "Heparanase expression is upregulated and is associated with increased VEGF expression in other retinopathy models, such as diabetic rats." (PMID 22773903, 2012).
HPSE also shares sentences with these, for which no sentence is quoted: multiple myeloma (21 papers); IgA nephropathy (4); renal failure (4); acute respiratory distress syndrome (3); cardiovascular disease (3); dyslipidemia (3); adenocarcinoma (2); anaplastic astrocytoma (2); asthma (2); Barrett esophagus (2); bladder urothelial carcinoma (2); breast adenocarcinoma (2); colon adenocarcinoma (2); coronary arterial disease (2); Crohn disease (2); diabetic retinopathy (2); embryonal rhabdomyosarcoma (2); gastric tumor (2); heart disease (2); malignant mesothelioma (2); medulloblastoma (2); pharyngeal carcinoma (2); Proteinuria (2); synovial sarcoma (2); Viral Diseases (2); abortion (1); acute lung injury (1); alcohol dependence (1); alopecia (1); amyloidosis (1).
A further 77 diseases each share a sentence with HPSE in 1 paper.